RHOA (ras homolog family member A)
Diseases named in the same sentence as RHOA in open-access papers (continued):
Sharing a sentence is not in itself a finding about the gene and the disease.
neurodevelopmental disorder (7 papers, 2014 to 2025). A behavioral and cognitive disorder with onset during the developmental period that involves impaired or aberrant development of intellectual, motor, or social functions. "Previous studies have demonstrated that disruptions in RhoA activity can lead to impaired synaptic plasticity, which is a hallmark of several neurodevelopmental disorders, including ASD." (PMID 39737255, 2024). "Together, these data provide evidence that TAOK2 is a neurodevelopmental disorder risk gene and identify RhoA signaling as a mediator of TAOK2-dependent synaptic development." (PMID 29467497, 2019). "Taken together, our findings support a critical role for GEF2 in regulating RhoA during cellular differentiation and suggest that disruptions in its function, through mutations or altered regulatory mechanisms, may contribute to neurodevelopmental disorders." (PMID 40581118, 2025). "Dysregulation of this gene has been linked to neurodevelopmental disorders, including mental retardation, and the transcription activity of MEF2C is regulated by RhoA signaling in a kinase cascade that also involves ERK6." (PMID 34433918, 2021). "This work identifies a mechanism that fine-tunes RhoA activity in migrating neurons and will help better understand the pathogenesis of human neurodevelopmental disorders." (PMID 24572910, 2014).
neurological disease (7 papers, 2014 to 2025). "The RhoA/ROCK2 pathway is a critical signaling pathway in neuronal apoptosis in neurological disorders." (PMID 40808924, 2025). "To date, several RhoA/ROCK inhibitors have been under development or in clinical trials as therapeutic agents for neurological disorders." (PMID 25374504, 2014). "Since multiple inhibitory signals converge onto the RhoA/ROCK pathway, identifying RhoA/ROCK inhibitors would be helpful in the treatment of neurological disorders." (PMID 25374504, 2014). "Further studies will consolidate the evidence linking RhoA/ROCK inhibitors to neurological diseases." (PMID 25374504, 2014). "The concept of treating neurological disorders with RhoA/ROCK inhibitors is considered as a rational therapeutic approach." (PMID 25374504, 2014). "We also discuss the potential therapeutic approaches of RhoA/ROCK inhibitors for various neurological disorders." (PMID 25374504, 2014). "In this review, we focus on the RhoA/ROCK signaling pathway in neurological disorders." (PMID 25374504, 2014). "Thus, RhoA/ROCK remains a promising molecular target for the treatment of neurological diseases." (PMID 25374504, 2014). "These insights not only enhance our understanding of TMP’s therapeutic mechanisms but also highlight the RhoA/ROCK pathway as a promising target for developing novel treatments for CIRI and related neurological disorders." (PMID 40495884, 2025). "In this study, we demonstrate that mutations within the TRPV4 ARD specifically disrupt interaction with a crucial regulator of the actin cytoskeleton, RhoA, providing a potential link between the function of TRPV4 in cytoskeletal dynamics and the pathogenesis of human neurological disease." (PMID 33664271, 2021).
hematologic malignancies (3 papers, 2014 to 2021). "At the same time, it is reported that RHOA deficiency affects platelet function and the structure of microtubules which is the potential association of RHOA to deregulation in human hematologic diseases." (PMID 27336623, 2016). "In the future, it is likely that molecular alterations, including the G17V RHOA mutation, will be increasingly incorporated into the diagnostic criteria for hematologic malignancies." (PMID 25310466, 2014). "Interestingly, TET2 mutations, which is frequently found in hematologic malignancies, was also found in all cases of p.Gly17Val RHOA mutation, suggesting a strong correlation between RHOA and TET2 dysfunctions." (PMID 33406731, 2021).
psychiatric disorder (3 papers, 2016 to 2020). A disorder characterized by behavioral and/or psychological abnormalities, often accompanied by physical symptoms. "The three main Rho GTPases—RhoA, Rac1, and Cdc42, together with their modulators, are known to be involved in many psychiatric disorders that affect the amygdala′s fear conditioning mechanism." (PMID 32858950, 2020).
skeletal dysplasia (3 papers, 2021 to 2025). Any Mendelian diseases that affects growth and development of the skeleton. "Indeed, we show that interaction with RhoA and promotion of neurite outgrowth are preserved with skeletal dysplasia mutations." (PMID 33664271, 2021). "Strikingly, neuromuscular disease- but not skeletal dysplasia-causing mutations disrupt TRPV4-RhoA binding and the capacity of TRPV4 to inhibit RhoA activation." (PMID 41338459, 2025).
central nervous system disorder (2 papers, 2019 to 2025). A disease involving the central nervous system. "The RhoA/ROCK signaling pathway plays crucial roles in many central nervous system disorders as an important downstream pathway of Lingo1." (PMID 39781463, 2025).
hematologic cancers (2 papers, 2014 to 2020). "In addition, when compared to the frequency of ACTB mutation in hematological cancers the frequency of RHOA mutations follows an analogous pattern." (PMID 32349449, 2020). "Using whole-exome and subsequent targeted sequencing, we recently identified G17V RHOA mutations in 60–70% of AITL and AITL-like PTCL-NOS cases but not in other hematologic cancers, including other T-cell malignancies." (PMID 25310466, 2014).
metabolic disorders (2 papers, 2014 to 2022). "Future studies in this area are expected to further expand the list of miRNAs targeting RhoA/ROCK pathways in metabolic diseases and elucidate their biological role at mechanistic level." (PMID 35769086, 2022).
neuromuscular disease (2 papers, 2023 to 2025). "Together, these results suggest that RhoA serves as an auxiliary subunit for TRPV4, regulating TRPV4-mediated calcium homeostasis and disruption of TRPV4-RhoA interactions can lead to TRPV4-related neuromuscular disease." (PMID 37353484, 2023).
retinal disorder (2 papers, 2016 to 2022). Any disease or disorder of the retina. "Injection of OPTC-overexpressing plasmids inhibited mRNA and the protein expression of RhoA/ROCK1 in the zebrafish model of hypoxia-induced retinopathy." (PMID 35006271, 2022).
brain diseases (1 paper, 2023). "Therefore, fine-tuning RhoA signaling to balance microglial reactivity may be beneficial for preserving neuronal plasticity in brain diseases that involve neuroinflammation." (PMID 37863874, 2023).
gastrointestinal tumours (1 paper, 2018).
gynecological tumors (1 paper, 2025). "Notwithstanding these significant strides, substantial knowledge gaps remain in the exploration of the ECT2 and RhoA/ROCK pathways and their intricate crosstalk mechanisms within gynecological tumors." (PMID 40655948, 2025). "The RhoA/ROCK pathway, in turn, propels the development of gynecological tumors via a complex network of multi-tiered cascades and extensive molecular crosstalk." (PMID 40655948, 2025). "Through comprehensive analysis and summary of the current research results, it is revealed that the ECT2/RhoA/ROCK signaling pathway and related crosstalk pathways play an important role in the occurrence, development, and metastasis of gynecological tumors." (PMID 40655948, 2025).
immune disorders (1 paper, 2019). "miR-31-5p was found to be underexpressed in T cells of patients with SLE; this molecule promotes the inhibition of the target gene RhoA and the downregulation of IL-2 expression and thus participates in immune disorders of SLE." (PMID 30836987, 2019).
vasculopathy (1 paper, 2019). "We investigated molecular mechanisms underlying the vasculopathy in CADASIL focusing on endoplasmic reticulum (ER) stress and RhoA/Rho kinase (ROCK)." (PMID 31647781, 2019).
RHOA also shares sentences with these, for which no sentence is quoted: diffuse large B-cell lymphoma (7 papers); Huntington disease (5); adult T cell leukemia (4); cholangiocarcinoma (4); hypertrophy (4); idiopathic pulmonary fibrosis (4); acute lymphoblastic leukemia (3); breast (3); cystic kidney (3); allergic rhinitis (2); encephalitis (2); experimental autoimmune encephalomyelitis (2); Glucose intolerance (2); goblet cell adenocarcinoma (2); intestinal tumor (2); meningitis (2); migraine (2); peripheral neuropathy (2); pheochromocytoma (2); Right ventricular hypertrophy (2); silicosis (2); skin cancer (2); small bowel cancers (2); spinal cord injury (2); thrombosis (2); thyroid (2); tongue cancer (2); Acidosis (1); acral melanoma (1); adrenal cancers (1).
A further 116 diseases each share a sentence with RHOA in 1 paper.